FTHL17 (ferritin heavy chain like 17)
Synonyms: CT38
Tractability: No criterion of Open Targets' tractability assessment is met for any kind of drug.
Gene: Protein-coding gene on chromosome X (31,071,233 to 31,072,041, reverse strand). Ensembl gene ENSG00000132446.
Gene Ontology:
Molecular function: protein binding; ferric iron binding; ferrous iron binding
Biological process: intracellular iron ion homeostasis; iron ion transport
Homologues: Orthologues: chimpanzee FTHL17 (96% identical), macaque FTHL17 (96% identical), pig FTHL17 (60% identical), Caenorhabditis elegans ftn-2 (45% identical), zebrafish zgc:56095 (40% identical), Caenorhabditis elegans ftn-1 (39% identical), Drosophila melanogaster Fer3HCH (37% identical), zebrafish zgc:172145 (25% identical). Paralogues in human: FTH1 (64% identical), FTMT (63% identical), FTL (46% identical).
Diseases named in the same sentence as FTHL17 in open-access papers:
FTHL17 is named in the same sentence as 10 diseases in open-access papers, as found by Europe PMC text mining. Sharing a sentence is not in itself a finding about the gene and the disease. The quoted sentences say what the papers report.
myocardial ischemia (2 papers, 2021). A disorder of cardiac function caused by insufficient blood flow to the muscle tissue of the heart. "The downregulation of CTB89H12.4 after myocardial ischemia results in an increase in the expression of miR-137 and miR-106b-5p, which sequentially activates the FTHL-17 and ANAPC11, respectively, with an increased translation and production of Nourin protein." (PMID 33670982, 2021). "The two networks, CTB89H12.4/miR-137/FTHL-17 and CTB89H12.4/miR-106b-5p/ANAPC11, were selected based on novelty, their direct interaction with Nourin protein, as well as association with myocardial ischemia." (PMID 33670982, 2021). "Results also support the ontology bioinformatics evidence that CTB89H12.4/miR-137/FTHL-17 and CTB89H12.4/miR-106b-5p/ANAPC11 networks synergistically regulate the Nourin protein expression in myocardial ischemia, and thus provide a novel molecular mechanism in ischemic heart disease." (PMID 33670982, 2021). "Specifically, Nourin-dependent miR-137 and FTHL-17 gene expression levels were significantly correlated with results obtained from ECHO or exercise ECG stress tests in determining the presence or absence of myocardial ischemia." (PMID 33919942, 2021).
colon cancer (1 paper, 2025). "FTHL17 is linked to cancer development, particularly in colon cancer." (PMID 40114930, 2025).
lung carcinoma (1 paper, 2017). "In the lung cancer cells, abnormal hypo-methylation of the Fthl17–0.6 kb to -0.3 kb region may be due to insufficient recruitment of DNA methyltransferases and/or their co-cofactors to this region, which may cause up-regulation of Fthl17 expression." (PMID 28207785, 2017). "Our results show that expression levels of the CTA gene, Fthl17, in lung cancer cells and in GSCs depend on methylation of the Fthl17 TSS-proximal region." (PMID 28207785, 2017). "The expression of Fthl17 in GSCs was significantly higher than that in a lung cancer cell line, KLN205." (PMID 28207785, 2017). "Fthl17 was more highly expressed in testis, a murine lung cancer cell line, KLN205, and in germline stem cells (GSCs) than in normal lung tissues." (PMID 28207785, 2017). "Together, the results suggest that hypo-methylation of different but adjacent regions immediately upstream of the Fthl17 gene contribute to differential expression levels in lung cancer cells and GSCs, and hypo-methylation of the TSS-proximal region may be critical for high level expression." (PMID 28207785, 2017). "The human CTA gene, Ferritin heavy polypeptide-like 17 (FTHL17), is expressed in bladder, breast and lung carcinomas and in testis, but not in other normal somatic tissues." (PMID 28207785, 2017).
Swyer syndrome (1 paper, 2025). "Swyer syndrome may be caused by SRY mutation (10%–15%), FTHL17, STARD8, SOX9, MAP3K1, NR5A1, and desert hedgehog gene (DHH) mutation as well as other unidentified genes." (PMID 41163677, 2025).
cancer (2 papers, 2017 to 2025). A tumor composed of atypical neoplastic, often pleomorphic cells that invade other tissues. "To address this, we assessed the epigenetic regulation of murine Fthl17 gene expression in cancer cells and germ cells." (PMID 28207785, 2017). "In this study, we addressed the role of epigenetic regulation, and DNA methylation in particular, in the regulation of Fthl17 gene expression in cancer cells and germ cells." (PMID 28207785, 2017). "The Ferritin heavy polypeptide-like 17 (Fthl17) gene is a member of the cancer/testis antigen gene family, and is preferentially expressed in cancer cells and in testis." (PMID 28207785, 2017). "Because FTHL17 was induced in human cancer cells after 5-aza-CdR treatment, we hypothesized that DNA methylation could regulate Fthl17 gene expression." (PMID 28207785, 2017). "Although functions of Fthl17 gene are so far unknown, the results suggest that Fthl17 is involved in cell proliferation through regulation by Spz1 and Plzf in cancer cells and in GSCs, respectively." (PMID 28207785, 2017). "Thus, the results indicate that DNA hypo-methylation of the -0.6 kb to 0 kb region plays a role in induction of Fthl17 gene expression in the cancer cells." (PMID 28207785, 2017). "Thus, hypo-methylation of the -0.3 kb to 0 kb region is correlated with the highest expression levels of Fthl17 in GSCs compared with testis and KLN205 cancer cells." (PMID 28207785, 2017).
FTHL17 also shares sentences with these, for which no sentence is quoted: colorectal adenoma (2 papers); breast carcinoma (1); ischemia (1); ischemic heart disease (1); tumor (1).